KIAA1755 (KIAA1755)
Synonyms: RP5-1054A22.3; quo
Tractability: Antibody: its Gene Ontology location is reachable by antibodies, with medium confidence.
Gene: Protein-coding gene on chromosome 20 (38,210,503 to 38,261,039, reverse strand). Ensembl gene ENSG00000149633.
Subcellular location (Human Protein Atlas): Nucleoli; Golgi apparatus; Vesicles
Gene Ontology:
Molecular function: guanyl-nucleotide exchange factor activity
Biological process: axon guidance
Cellular component: cytoplasm; extrinsic component of membrane; plasma membrane
Genetic constraint (gnomAD): Loss-of-function variants: 63 observed, 81.44 expected, observed/expected ratio (o/e) 0.77, 90% interval 0.63 to 0.95. The upper end of that interval is the gene's LOEUF score, 0.95, which puts it in group 4 of 6, group 1 being the genes least tolerant of losing a copy. Missense variants: 1,522 observed, 1,498.4 expected, observed/expected ratio (o/e) 1.02, 90% interval 0.97 to 1.06. Synonymous variants: 600 observed, 605.92 expected, observed/expected ratio (o/e) 0.99, 90% interval 0.93 to 1.06.
Homologues: Orthologues: chimpanzee KIAA1755 (97% identical), macaque KIAA1755 (93% identical), dog KIAA1755 (75% identical), pig KIAA1755 (75% identical), guinea pig KIAA1755 (70% identical), rabbit KIAA1755 (68% identical), mouse D630003M21Rik (64% identical), rat Kiaa1755 (55% identical). Paralogues in human: PLEKHG4B (23% identical), ARHGEF40 (23% identical), PLEKHG4 (16% identical), KALRN (13% identical), TRIO (13% identical), TIAM2 (11% identical), TIAM1 (10% identical), MCF2L (10% identical), MCF2L2 (8% identical), MCF2 (8% identical), SPATA13 (7% identical), SESTD1 (6% identical), and 10 more.
Diseases named in the same sentence as KIAA1755 in open-access papers:
KIAA1755 is named in the same sentence as 6 diseases in open-access papers, as found by Europe PMC text mining. Sharing a sentence is not in itself a finding about the gene and the disease. The quoted sentences say what the papers report.
breast carcinoma (1 paper, 2024). "Research has indicated that the high expression of Kiaa1755 is present in breast cancer patients, but our results revealed that the expression of Kiaa1755 is upregulated in MDA-MB-231 cells under hypoxia, which finding should be further studied in the future." (PMID 39194515, 2024).
endometrial cancer (1 paper, 2025). Primary or metastatic malignant neoplasm involving the endometrium (mucous membrane that lines the endometrial cavity). "This study is the first to explore the prognostic significance and immune activation roles of BATF, CD3G, KIAA1755 and CCL5 in endometrial cancer." (PMID 40356925, 2025).
essential hypertension (1 paper, 2019). Hypertension that presents without an identifiable cause. "For example, LoF mutations in the gene KIAA1755 were identified to elevate the levels of eicosapentaenoate (p-value = 5E-14), an essential fatty acid clinically identified to increase essential hypertension." (PMID 31113383, 2019).
cardiovascular disease (1 paper, 2023). "Moreover, based on the T2D knowledge portal, the genomic region in which LncTGM2 is located (also containing TGM2, RPRD1B and KIAA1755 genes) has been associated with several metabolic and glycemic traits, including cardiovascular disease related parameters, cholesterol and type 2 diabetes." (PMID 36824360, 2023).
KIAA1755 also shares sentences with these, for which no sentence is quoted: cancer (1 paper); glioma (1).